BRAF (B-Raf proto-oncogene, serine/threonine kinase)
Diseases named in the same sentence as BRAF in open-access papers (continued):
Sharing a sentence is not in itself a finding about the gene and the disease.
melanoma (continued). "In BRAF-mutated melanomas, we also found a significantly higher frequency of shiny white structures that reflect de novo synthesis or remodeling of collagen in the papillary dermis as a response to melanoma of the fibroblast and stroma." (PMID 40867317, 2025). "Studies have shown that approximately 80% of BRAF point mutations detected in nearly 50% of melanomas result from the 1796T>A missense mutation, leading to the V600E amino acid alteration." (PMID 41142596, 2025). "BRAF gene amplification and splicing variants represent key mechanisms of acquired resistance to BRAFi in melanoma treatment." (PMID 40872623, 2025). "It exhibits potential inhibitory activity against melanoma and colorectal cancer cell lines with BRAF mutations, particularly those harboring BRAF and NRAS mutations." (PMID 40781327, 2025). "Mutations in BRAF, especially the V600E mutation, are common in various types of cancer, including melanoma, colorectal cancer, and thyroid cancer." (PMID 40317918, 2025). "Mutations in BRAF occur in ∼50% of melanomas, with the vast majority introducing a phosphomimetic V600E substitution (BRAFV600E) that confers constitutive kinase activity." (PMID 39636745, 2025). "Adjuvant therapy with Nivolumab resulted in a 12‐month event‐free survival rate (EFS) of 52.2% and 62.4% in patients with a BRAF V600 mutation and patients with BRAF WT melanoma respectively." (PMID 41342263, 2025). "Human melanoma is thought to be caused by environmental ultraviolet light exposure resulting in genomic mutations, with about half involving mutations of the BRAF and NRAS genes." (PMID 41012800, 2025). "BRAF mutations, which are found in about 60% of melanomas, were initially identified in 2002 in human malignancies." (PMID 41142596, 2025). "Melanoma is the most aggressive form of skin cancer, with more than half of cases harboring BRAF mutations." (PMID 40617808, 2025). "Most patients with CLL and melanoma are diagnosed with pathologic Stage III disease or lower, and a literature review has demonstrated that melanoma in patients with CLL has variable incidences of BRAF and NRAS mutations." (PMID 39940799, 2025). "Germline BRAF mutations are found in the majority of melanomas, thyroid cancers, and histiocytic tumors, as well as in a small proportion of lung and colorectal cancers." (PMID 40896440, 2025). "Metastatic melanoma treatment currently relies on immune checkpoint inhibitors (ICIs) and targeted therapies, with BRAF and MEK inhibitors used in patients with BRAF V600E mutations." (PMID 41010656, 2025). "BRAF p.V600E represents the most frequent oncogenic mutation in BRAF and is found in about half of melanomas, 40% of papillary thyroid cancers, and about 10% of colorectal cancers." (PMID 40634537, 2025). "This is illustrated in the combination of a BRAF inhibitor dabrafenib with a MEK inhibitor trametinib, which suppresses paradoxical reactivation and resistance observed in patients with BRAF-mutated melanoma treated with dabrafenib alone." (PMID 40459126, 2025). "While targeted kinase inhibitors have improved outcomes for patients with BRAF‐mutated melanomas, their efficacy is often short‐lived, and effective treatments for other mutations, such as NRAS, remain scarce." (PMID 41199020, 2025). "A phase I/II clinical trial (NCT03101254) investigated the efficacy of LY3022855 in treating advanced melanoma with BRAF gene mutations." (PMID 40918451, 2025). "In BRAF-mutated high-risk melanoma, targeted therapy (BRAF/MEK inhibitors) and checkpoint inhibitor (CPI) immunotherapy have durable benefits as first-line (1L) adjuvant therapy." (PMID 39560953, 2025). "Tovorafenib has shown single-agent activity in adult patients with BRAF-mutated melanoma in a phase I trial." (PMID 40111124, 2025).
melanoma (continued). "In summary, mutated BRAF in melanoma not only activates signaling pathways that promote cell proliferation but also induces complex metabolic reprogramming that supports the high biosynthetic demands of tumor cells." (PMID 40872623, 2025). "eCas12f1 induced cell death in breast cancer cells by disrupting PLK1 and notably eCas12f1 effectively disrupted cancer-specific genes by recognizing BRAF mutations in the malignant melanoma cells." (PMID 39809780, 2025). "Approximately 50% of melanomas exhibit BRAF V600-mutations, involving the substitution of valine in position 600 with glutamic acid (V600E, up to 80–90% cases), lysine (V600K, 10–21%), arginine (V600R, 5%) or aspartate (V600D < 5%)." (PMID 40872623, 2025). "The BRAF gene, known for somatic activating mutations, has been identified in melanomas (>60%) and other cancer types, with the V600E substitution in exon 15 being predominant." (PMID 40002790, 2025). "For instance, vemurafenib, a B-Raf proto-oncogene (BRAF) inhibitor, is used to treat melanoma caused by BRAF mutation." (PMID 40078288, 2025). "The aims of the study were to assess the clinical, histopathological, and dermoscopic features of melanoma to identify their correlation with BRAF, NRAS, and cell cycle genes’ mutational status in melanoma." (PMID 40867317, 2025). "Another study on triple therapy including the PI3K inhibitor buparlisib, BRAF inhibitor, and MEK inhibitor, showed a low clinical benefit in advanced BRAF V600-mutated melanoma (NCT02159066)." (PMID 40399946, 2025). "Our analysis showed that patients with a BRAF V600 mutation treated with adjuvant anti‐PD1 monotherapy had a worse RFS than patients with BRAF WT melanoma." (PMID 41342263, 2025). "The inhibition of mutated BRAF proteins by selective kinase inhibitors represents the most significant breakthrough in targeted melanoma therapy to date." (PMID 40932870, 2025). "(2015) found a BRAF mutation in 6% of canine melanomas, signifying the potential for targeted therapies in such cases." (PMID 41394861, 2025). "In melanoma, BRAF-mutated cells exhibit enhanced polyamine transporter activity, leading to increased resistance to BRAF inhibitors." (PMID 40444051, 2025). "Multiple studies have reported that ERBB-3 becomes phosphorylated when BRAF V600E-mutated melanoma cells are treated with BRAFi or MEKi." (PMID 40872623, 2025). "Mutations in the BRAF kinase are observed in ∼40–60% of melanoma patients, and other frequent melanoma subtypes involve activating mutations in RAS isoforms (20–30% of patients) or loss of NF1 (10–15%)." (PMID 39658088, 2025). "Current clinical protocols for melanoma incorporate biomarkers for targeted therapy (e.g., BRAF mutation status) and immunotherapy (e.g., PD-L1 expression) but none are established for this novel approach." (PMID 41235238, 2025). "The KIT/NRAS/BRAF signaling pathway is the dominant pathway in both melanocytes and melanomas, which is why mutations in these oncogenes occur with such frequency." (PMID 40361349, 2025). "Therapies targeting BRAF can inhibit the development of melanoma with BRAF mutations and enhance survival rates, though acquired resistance inevitably arises." (PMID 41198656, 2025). "Targeted drug therapy using vemurafenib has revolutionized the treatment of patients with inoperable melanoma harboring BRAF gene mutation through significantly-improved overall survival and progression-free survival rates." (PMID 41145465, 2025). "In melanoma, activating BRAF mutations—most notably BRAFV600E and BRAFV600K—drive constitutive MEK activation and sustained ERK phosphorylation, leading to aberrant oncogenic signaling independent of upstream receptor stimulation or external mitogenic cues." (PMID 41302945, 2025). "The use of MEK inhibitor and PD-1 inhibitor combination therapy has been investigated thoroughly in patients with advanced melanoma, specifically among patients with BRAF V600 mutations." (PMID 40004731, 2025).
melanoma (continued). "A defining feature of BRAF-mutant melanoma is the upregulation of proliferation-associated genes, such as MYC, CCND1, and E2F1, which synergistically fuel the unchecked growth of melanoma cells." (PMID 40872623, 2025). "Another study identified acquired NRAS and PIK3CA mutations in cfDNA samples obtained from melanoma patients who had progressed on BRAF/MEKi." (PMID 39859576, 2025). "In melanoma, the common BRAF mutation upregulates IL - 8 expression via the MAPK pathway, fostering inflammation and an immune - suppressive microenvironment." (PMID 41040520, 2025). "We observed a significant increase in GSK3β mRNA expression in A375 BRAF-mutated melanoma cells during the development of BRAF resistance." (PMID 40184329, 2025). "Increased TAMs and PD-L1 are associated with melanoma resistance to the single-agent BRAF (Serine/threonine-protein kinase B-raf) inhibitor dabrafenib or in combination with MEK (Mitogen-activated protein kinase) inhibitor trametinib." (PMID 40399946, 2025). "We have demonstrated that introducing PMCA4b to a BRAF mutant melanoma cell line resulted in a severe loss of integrin β4 expression." (PMID 40075218, 2025). "The detection of this mutation in melanoma is a favorable prognostic marker, as targeted therapies such as BRAF and MEK inhibitors are known to significantly improve survival in carriers of this mutation." (PMID 40977811, 2025). "Meanwhile, in melanoma, approximately 66% of cases harbor BRAF mutations, yet the relationship between BRAF and TLS remains poorly characterized." (PMID 40475020, 2025). "Although BRAF mutations are less common in CCA than in melanoma or thyroid cancer, they activate the MAPK/ERK and MEK signaling pathways, promoting tumor proliferation and survival, and thus represent promising therapeutic targets." (PMID 41008893, 2025). "When discussing melanoma and BRAF resistance, the PI3K pathway is often implicated as a bypass mechanism conferring survival following targeted therapy." (PMID 40510029, 2025). "For dabrafenib–trametinib, these discussions should also consider the DMFS and RFS benefits and potential OS benefit for patients with BRAF V600E-mutated melanoma [I, A]." (PMID 39550033, 2025). "Compounds extracted from Caulerpa racemosa were tested on melanoma A375 cell line exhibiting BRAF-V600E mutation and on B16-F10 murine melanoma cell lines." (PMID 41470117, 2025). "But due to the similarities between MP and malignancy, it is crucial in patients at risk for MP development—including BRAF/MEKi treated melanoma patients—to be aware of this condition." (PMID 40310541, 2025). "Based on these results, adjuvant dabrafenib–trametinib is an SoC adjuvant treatment option for BRAF V600E-mutated stage III melanoma and is approved by the EMA." (PMID 39550033, 2025). "We combined this mutant Prex2E22A,N204A (Prex2gd) allele with our BRAF PTEN melanoma model (Tyr-CreERT2BrafV600E/+Ptenfl/+Prex2gd/gd – BRAF PTEN PREX2-GD)." (PMID 39636745, 2025). "BRAF-mutated melanomas carry a worse prognosis and a higher metastatic potential compared to wild-type melanomas." (PMID 40332392, 2025). "These structures can be tailored with ligands, antibodies, or peptides to target melanoma-specific biomarkers, such as BRAF mutations and MC1R, enabling selective drug delivery while minimizing off-target effects." (PMID 40142960, 2025). "For instance, BRAF/MEK inhibitors can mitigate the immunosuppressive milieu often associated with advanced melanoma, facilitating increased T cell infiltration and enhancing anti-tumor responses triggered by ICIs." (PMID 40963596, 2025).
melanoma (continued). "For patients with advanced melanoma and a BRAF mutation, additional treatments targeting this mutation have been approved, such as vemurafenib (plus cobimetinib), dabrafenib (plus trametinib), and encorafenib plus binimetinib." (PMID 39985400, 2025). "Detecting BRAF mutation is vital in advanced melanoma patients for the effective use of BRAF–MEK inhibitors." (PMID 40004220, 2025). "Melanoma, a highly immunogenic malignancy, harbors BRAF mutations in 40–60% of cases, which are associated with poor prognosis." (PMID 40659866, 2025). "In melanoma, BRAF inhibitor therapy can trigger secondary NRAS or MEK mutations, leading to compensatory MAPK pathway activation and tumor regrowth." (PMID 41417875, 2025). "Previous research suggests that many lesions diagnosed as an SM or AST, that developed distant metastases and resulted in a fatal outcome, were actually conventional melanomas harboring BRAF or NRAS mutations, frequently accompanied by TERT-p alterations." (PMID 40227833, 2025). "Third, the pro-apoptotic activity of RGD-apoptins needs to be tested in BRAF-mutated melanoma cells and in normal melanocytes." (PMID 41465443, 2025). "BRAF inhibitor treatment has emerged as a standard of management for patients with advanced BRAF V600-mutant melanoma, but the mechanism of SJS/TEN associated with BRAF inhibitor therapy remains incompletely understood." (PMID 40936888, 2025). "Genetically, male melanoma patients exhibit higher mutation rates in BRAF and NRAS, along with lower expression of ERβ, while elderly patients tend to have increased NRAS mutations and decreased BRAF mutations." (PMID 41085102, 2025). "Autophagy can serve as an effective escape mechanism for cancer, contributing to the development of resistance in various cancer types such as BRAF-mutated central nervous system tumors, melanoma, NSCLC, bladder cancer, and thyroid cancer." (PMID 39885142, 2025). "Approximately half of advanced melanomas harbor mutations in the BRAF gene, which are linked to an increased frequency of BMs." (PMID 40076927, 2025). "The prevalence of mutations in BRAF are less common in mucosal melanomas meaning that a lower proportion of patients are eligible for targeted immunotherapy." (PMID 41170453, 2025). "IL-7 is linked to disease progression in melanoma, with lower serum levels observed in patients, especially those with BRAF mutations." (PMID 40636453, 2025). "Another Phase 1b clinical trial reported that the selective ERK1/2 inhibitor, MK-8353, demonstrated substantial therapeutic efficacy both as monotherapy and in combination treatments in BRAF V600-mutated melanoma." (PMID 40723336, 2025). "This approach is particularly relevant because constitutive gene activity can arise not only from mutations but also from gene fusions, as demonstrated for BRAF fusions in various solid tumors, including melanoma." (PMID 40737104, 2025). "BRAF mutations are critical drivers in cancers such as melanoma, colorectal cancer, and non-small-cell lung cancer." (PMID 40332392, 2025). "V600E is the most frequently occurring BRAF mutation in melanoma, and it also has the highest association with BMs." (PMID 40076927, 2025). "Most prominently, the V600E mutation in BRAF causes malignant melanoma, papillary thyroid cancer, and other malignancies." (PMID 41072765, 2025). "In this study, we sought to explore key factors and mechanisms driving drug resistance against vemurafenib treatment in BRAF-mutated melanoma." (PMID 41145465, 2025). "BRAF mutations, particularly the BRAF V600E, are the most common molecular feature of melanoma, playing a pivotal role in the pathogenesis." (PMID 41315179, 2025). "The trial demonstrated the efficacy of vemurafenib across various BRAF-mutated non-melanoma cancers, providing proof of concept for histology-independent, molecularly guided therapies." (PMID 41153346, 2025).
melanoma (continued). "Somatic mutations in the V600 codon of BRAF have been found in 35–50% of melanomas and the amino acid substitution from a valine to a glutamic acid at codon 600 (V600E) accounts for 74–92% of BRAF mutations in melanoma." (PMID 40867317, 2025). "In melanoma, BRAF mutation is the most frequent alteration (50% of melanoma tumors) leading to abnormal activation of the RAS/RAF/MEK/ERK signaling pathway." (PMID 39115053, 2025). "In another study, BRAF mutation was prospectively identified in 37/99 (37%) stage III melanoma patients, from a single institution through ddPCR assays in plasma samples." (PMID 39859576, 2025). "A meta-analysis observed that the presence of BRAF mutations was associated with poorer prognosis and overall survival in melanoma patients, although there was high heterogeneity between the studies." (PMID 41010758, 2025). "In several preclinical studies, metformin has demonstrated antitumor activity against melanoma, especially in cases with BRAF mutations." (PMID 40331942, 2025). "Among the known pathogenic genes of melanoma, BRAF is the most frequent mutant driver gene, endowing the tumor cells with a more aggressive phenotype by constitutively activating the MAPK pathway." (PMID 40592836, 2025). "These molecules target genetic abnormalities that cause melanoma, such as BRAF mutations, by silencing oncogenes or restoring the functions of tumor suppressor genes." (PMID 40142960, 2025). "For this purpose, melanoma cell lines bearing a defined BRAF mutation (A375 BRAF-V600E) were treated with the small molecule BRAF inhibitor Dabrafenib (GSK2118436) until developing resistance." (PMID 40184329, 2025). "In conclusion, this study increases our understanding of the epidemiology of BRAF mutations in melanoma." (PMID 40902091, 2025). "In melanoma, autophagic activity is regulated by oncogenic signals such as BRAF and NRAS and is closely associated with tumor metabolic reprogramming." (PMID 40497999, 2025). "Clinical studies have shown that vemurafenib induces partial or complete tumor regression in patients with BRAF V600E-mutated melanoma." (PMID 40861441, 2025). "Targeted therapy with BRAF and MEK inhibitors has become the standard treatment of patients with BRAF V600 mutation-positive melanoma with great efficacy, especially when used in combination." (PMID 41515422, 2025). "Dabrafenib, used in BRAF V600E-mutant melanoma, has been linked to ocular side effects, particularly when combined with MEK inhibitors." (PMID 41568391, 2025). "For example, BRAF inhibitors have been commonly used to treat melanomas, showing selective effects in tumors with BRAF V600 mutations." (PMID 41199020, 2025). "The V600E point mutation in BRAF drives more than 50% of malignant melanoma and is also found in thyroid, lung, and many other cancers." (PMID 41072765, 2025). "Telmisartan, an angiotensin II type 1 receptor (AT1R) antagonist, possesses cytotoxic activity towards BRAF-mutated melanoma cell lines." (PMID 41515422, 2025). "On the other hand, NRG1 is highly expressed by dermal fibroblasts and cancer-associated fibroblasts in melanomas with BRAF mutations, promoting cell growth and resistance to BRAFi." (PMID 40872623, 2025). "Apart from this, reported research on BRAF inhibitors in BRAF-mutated pancreatic adenocarcinoma is limited to a handful of case reports or brief mentions within larger analyses of all non-melanoma cancers." (PMID 41367868, 2025). "The BRAF gene mutation plays a pivotal role in tumorigenesis, tumor development, and prognosis across various cancer types, including malignant melanoma, colon cancer, NSCLC, thyroid papillary carcinoma, and serous ovarian cancer." (PMID 41480531, 2025).